IL6 (interleukin 6)
Diseases named in the same sentence as IL6 in open-access papers (continued):
Sharing a sentence is not in itself a finding about the gene and the disease.
infection (continued). "The splenocytes’ release of TNF-α and IL-1β was increased by 69% and 224.8%, respectively (all, &p < 0.05) while IL-6 and IFN-γ release was not significantly changed when mice were prophylactically immunized with V2/4 vaccine before infection (vs. non-vaccinated/infected mice)." (PMID 34497271, 2021). "Interestingly, while IL-6 transcript upregulation was dependent on T3SS-1, neither T3SS-1mut nor T3SS-2mut infection stimulated significant IL-6 protein production compared to that of PBS-injected HIOs." (PMID 34006652, 2021). "In our study, infection of RD-A cells with the genotypes D, G and C with 1 MOI could not produce pro-inflammatory cytokines such as IFN-γ, TNF-α IL-6, IL-8, IP-10, MCP-1 as tested by Multiplex ELISA and validated by real time PCR." (PMID 34493781, 2021). "Our results show that IL-4, IL-6, IL-8, IL-10, IL-12P70, IL-1β, IL-2, IFN-γ, TNF-α, TNF-β and IL-17A are in the lungs The expression level of bacterially infected individuals was higher than that of patients without any infections (P<0.05)." (PMID 34925324, 2021). "At 5 h post-infection, infected or non-infected PHT, produced TNFα, IL-8 and IL-6." (PMID 34367171, 2021). "Intestinal macrophages isolated from mice in the absence of infection or inflammation do produce low levels of cytokines classically described as proinflammatory, such as TNF and IL6, in response to TLR stimulation but, crucially, they also produce IL-10 to temper their activity." (PMID 33465156, 2021). "Moreover, the plasma levels of IL-2, IL-6, IL-8, IL-10, and TNF-α, observed in severe infection, are prominently greater than those in nonsevere infection." (PMID 32299202, 2020). "The decreased production of IL-1β and IL-6 in phagocytes was likely not only due to active inhibition by DAT alone, as co-treatment with DAT-coated beads did not decrease production of these cytokines during WT infection when compared to control beads." (PMID 32695111, 2020). "In vivo, IL-17A and IL-6 are upregulated in early-stage MAP-infected lesions (Grade 1), but not in late infection/clinical Johne's disease lesions, suggesting that Th17 responses to MAP are subject to the same T cell exhaustion that occurs with Th1-like cells in late clinical JD." (PMID 32258066, 2020). "In addition, our study showed that infection with L. infantum did not determine a significant difference in the production of TNF-α and IL-6." (PMID 31961876, 2020). "In addition, UV-inactivated HCMV, which does not undergo viral transcription and translation after infection, induced higher levels of IFNB1, ISG56, and IL6 mRNA than un-treated HCMV." (PMID 31107917, 2019). "Taken together, these data indicate that IAV itself, but not IAV-induced cytokines including IL-6 or newly synthesized viral proteins, might trigger SOCS3 expression at the early infection stage." (PMID 31474976, 2019). "Apart from IL-6 (miR-9 target), PIK3CA, and CAV1 (miR-124 target), no other target gene has been found to be reported previously either in a case of JEV infection or in infection by any other flaviviruses." (PMID 31578247, 2019). "Similarly, the PRV-induced inflammatory response is restricted to the area of infection, the footpad, as the virus does not activate DRG neurons to produce G-CSF and IL-6 in the absence of TLR2." (PMID 31675371, 2019). "Similarly, at day 84 post-infection, no clear difference was observed in the concentration of IFN-γ, IL-1β, TNF-α, IL-12, IL-6, IL-10 and IL-4 in the both groups of mice." (PMID 31801478, 2019). "While infection with an MCMV lacking m152 induced elevated type I IFN responses both in vitro and in vivo, leading to tighter host control of viral transcription at early time points post‐infection, the NF‐κB‐dependent IL‐6 response was not affected by m152." (PMID 30696688, 2019).
infection (continued). "However, the systemic concentrations of some pro-inflammatory cytokines (IL-6 and CCL2), but not all (TNF-α, IL-1α, and IL-1β), were slightly over-induced in Ripk1LPC-KO mice at late stage of infection (72 hpi)." (PMID 30622241, 2019). "When PERP knockdown followed by treatment with MY1WT in dGCs, there is an opposite trend emerged of the mRNA expression level of TNF-α (P <0.05), however, overexpression of PERP or knockdown PERP showed no significant mRNA level change of IL-6, IL-1β, TNF-α, and IFN-γ during MY1ΔsipC infection." (PMID 31565575, 2019). "At three months post-infection with low dose EBV, serum levels were biased towards proinflammatory cytokines and chemokines like TNFα, IL-8, and IL-6, while IFNγ and IL-10 were not significantly elevated, in contrast to what we observed after five weeks of high dose EBV infection." (PMID 31145756, 2019). "Interestingly, IL-6, IP-10, CXCL5, and MIP1-β levels were higher 12 weeks post infection in groups receiving no treatment, whereas all other time points were similar between each of the three groups (data not shown)." (PMID 29795025, 2018). "Similarly, in brain injured patients who did not develop infection, 5,6-DHET and 8,9-DHET levels increased over the duration of ICU stay and IL-6 levels fell." (PMID 30283005, 2018). "However, EV Y inoculation prior to infection did not alter the levels of IFN-γ, MCP-1, or IL-6 in the plasma of infected mice at 12 dpi compared with those in the plasma of PBS-inoculated infected mice." (PMID 29755471, 2018). "Through the first four days of infection and co-treatment with eritoran, viral titers did not notably decrease; however, pro-inflammatory cytokines and chemokines, such as TNF-α, IL-1β, IL-6, and CXCL1 were mitigated during this early infection and the IAV infection resolved more rapidly." (PMID 29988424, 2018). "While IL-6 induced strong STAT3 phosphorylation, no phosphorylation was observed in cell infected with either the WT or ΔespO, suggesting that STAT3 phosphorylation is not a direct cell response to infection." (PMID 30365535, 2018). "Infection with the ATCC 25923 strain (CATCC and DATCC) did not alter IL-6 levels, but treatment with multiple doses of insulin increased IL-6 production (7- to 6-fold) in the PeLF from infected diabetic rats (DATCC+i2) compared with that of non-insulin-treated animals (DATCC)." (PMID 30705678, 2018). "The lack of immediate increase in both IL6 and TNF following miR-122 inhibitor infection shows that these cytokines possibly are not among direct targets of miR-122 and miR-122 inhibition increases these cytokines through indirect effect on some other elements of hepatic signal transduction." (PMID 30024933, 2018). "Measurement of the concentration of inflammatory cytokines in cell supernatants allowed us to observe significant decreases in the level of IL-8, IL-1b, IL-6, TNF-alpha and IL-10 in cells treated with VPA before or after infection with DENV serotype 2, without affecting cell viability." (PMID 29986388, 2018). "The difference in the profile of the cytokine response between cells infected with live H5N1 and those exposed to inactivated virus suggests that components of the viral envelope can initiate expression of IL-6 and CXCL8 independent of infection or viral replication." (PMID 28494003, 2017). "Data obtained from ELISA demonstrated that enrofloxacin and toltrazuril increased IL-6 and MIF production in BeWo cells infected by T. gondii, regardless of strain, while in the absence of infection, enrofloxacin induced only high IL-6 levels and toltrazuril triggered high IL-6 and MIF levels." (PMID 28798905, 2017). "IL-17 plays a crucial role in resistance to infection and absence of this cytokine in mice has increased T. cruzi in the liver, heart and kidney and decreased inflammatory cytokines such as IFN-γ, TNF-α and IL-6." (PMID 29255475, 2017).
infection (continued). "Finally, overnight infection did not trigger significant changes in production of TGFβ-1, IL-8, IFN-γ, and IL-6 by the co-culture." (PMID 28345602, 2017). "The levels of IFN-γ, IL-4, IL-5, IL-6 and TNF-α were measured in the plasma of HP and non-HP PbNK65 1556Cl1-infected Hsd11b1Del/Del and WT mice at 21 to 24 days (HP) or 28 days (non-HP) after infection." (PMID 29062028, 2017). "No significant trends were observed in IL-6, MCP1 or IFNγ at day 12 post-infection." (PMID 28270815, 2017). "Moreover, omentin concentrations did not correlate with markers of inflammation or infection such as C-reactive protein (CRP), procalcitonin (PCT), and interleukin-6 (IL-6)." (PMID 27867249, 2016). "Whereas the secretion of IL-6 by spleen cells was unaffected by the lack of IL-22, the splenic production of IFN-γ, TNF and IL-10 was increased in IL-22−/− mice compared to wild-type mice at day 14 post infection." (PMID 27650379, 2016). "Smooth muscles and cardiomyocytes as well as infection parameters, such as CRP, IL-6, and procalcitonin, could be further examined to rule out effects on these tissues." (PMID 28050282, 2016). "However, there were no HIF-1α-dependent differences in lung cytokine secretion, indicating that lung epithelial HIF-1α is not required to induce IL-1β, IL-6, CXCL1, CXCL2, or MIP-3α secretion during infection." (PMID 27624128, 2016). "Remarkably, elevated IFN-γ, IL-6 and MCP-1 levels could be determined at day 6 post CCUG 30485 strain infection (p<0.05–0.001), that did, however, not differ from ileal secretion in C. jejuni infected mice." (PMID 27438014, 2016). "IL6 has been considerably induced in the spleen of the GPV-infected group, and its expression level rose clearly both in immune-related and non-immune tissues during TMUV infection, most likely due to the stronger virulence of the TMUV strain." (PMID 27150912, 2016). "The κ-carrageenan could decrease the IL-6 and TNF-α mRNA levels but promote the IL-1β mRNA synthesis with or without SW731 infection." (PMID 25969984, 2015). "In the present studies, we profiled the pro-inflammatory (IL-6) and anti-inflammatory (TGF-β4) cytokine mRNA expression in the cecum of chickens over the first 14 days post-infection with S. Enteritidis and compared the results to the non-infected control birds." (PMID 26664962, 2015). "However, monocyte-derived dendritic cells do not secrete proinflammatory cytokines of TNF-α, IL1β, IL6, IL10, or IL2, IFN-γ, or IL12 after infection with Ebola virus, though there are higher levels of certain chemokines (notably IL8 and MCP1)." (PMID 25592846, 2015). "Conversely, 15 days after treatment of blood stage infection with chloroquine, splenocytes showed spontaneous in vitro expression of TNFα, IL2, IL6, IL10, and IL12, but not IFNγ, and stimulation with P. falciparum pRBC blocked the expression of all these cytokines." (PMID 25890318, 2015). "Interestingly, although IFN β, IL6 and IP10 mRNA production are almost equivalent at 8 hours post-infection when comparing infected and non-infected cells, the levels were significantly higher in Atg5 and Atg7 knock-down cells relative to control cells." (PMID 23320079, 2013). "Finally, there was no infection by Human Herpes Virus 8 (HHV8), which contains an IL-6 homologous gene." (PMID 23432807, 2013). "Kinetics of virus replication, transcription factor (c-Jun, p50 and IRF-3) activation and immune response gene (IL-6, IL-1beta, IFN-alpha and Mx) expression were studied at four different time points (6, 12, 24 and 48 hours) post infection and compared to non-infected controls." (PMID 24252391, 2013). "The complete inhibition of infection in the presence of 10% autologous serum or UV-irradiation was further confirmed by the complete absence of IFN-β and IL-6 production by RSV exposed A549 cells, which depends for epithelial cell lines on the access of viral RNA to intra-cellular RLR." (PMID 24303065, 2013).
infection (continued). "Thus, significantly lower levels of circulating serum IL-6, IFN-γ, KC, IP-10 and MCP-1 were detected at 72 h of infection in DCs-depleted than in non-depleted mice." (PMID 23802100, 2013). "Interestingly, the IL-6 and IL-1β expression in CEH without trypsin after infection were far lower compared to expression observed with trypsin." (PMID 24252391, 2013). "In contrast to infection with UV-HCMV, ganciclovir pretreatment of the cells did not prevent STAT3 activation in PHH infected with HCMV, indicating that STAT3 activation, like IL-6 production, did require early steps of viral replication." (PMID 23555719, 2013). "Moreover, we performed logistic regression and ROC analyses for post-operative IL-6 and TNF-α levels; however, they were not important predictors of infection (data not shown)." (PMID 23520452, 2013). "Stimulation of IL-6, IL-1β, and IL-17, independent of ClpV-mediated TNFα production, suggests that the T6SS may play a role in recruiting immune cells to the site of infection." (PMID 23071529, 2012). "Of those tested Cdc42ep3 (CDC42 effector protein), ARHGDIB (Rho GDP dissociation inhibitor (GDI) beta), Acta2 (Alpha actin 2), Egr2 (Early growth response 2), IL-6 (Interleukin 6) and Vav3 (vav 1 guanine nucleotide exchange factor), were induced by EPEC infection but not by infection with EPEC Δtir." (PMID 21490959, 2011). "The lung cell IL-6 and IL-17 production was higher in the BCG-vaccinated non-boosted mice (451 ± 33 pg/mL) than in the BCG-vaccinated/rHBHA-boosted (271 ± 37) and in the PBS control mice (133 ± 7 pg/mL) after i.n. infection." (PMID 21647410, 2011). "In order to evaluate whether PbAOX suppression could alter the cytokine profile in alveolar macrophages, we determined the gene expression of IL6, IL10, IL12p40, and TNF-α during infection of non-activated and IFN-g-activated alveolar macrophages." (PMID 22039556, 2011). "We did not assess other markers (for example, IL-6, IL-8, TNF-α, endotoxin, serum amyloid A, or neopterin) that could be considered to augment the diagnosis of infection in neutropenic patients, as explored by others." (PMID 19291300, 2009). "At day 4 following CB4 infection of WT NOD mice, we observed significant increases compared to uninfected controls in the levels of both TNF-α and IL-6 and to a lesser extent IFN-γ Little to no production of IL-4, IL-5, IL-10, IL-12p70 was observed following infection (data not shown)." (PMID 19122812, 2009). "However, production of IL-6 and type I IFN in the absence of TAK1 was normal in response to SeV Cm infection." (PMID 19479062, 2009). "Despite inducing robust secretion of proinflammatory mediators such as IL-6, IL-8, and TNF, RSV infection does not elicit a marked increase in IL-1β levels in bronchoalveolar lavage fluid, nasopharyngeal secretions, or systemic circulation during the early phase of infection." (PMID 41576161, 2026). "In the current study, the high CD38 expression in old murine BMMs after infection with oral pathogens was not directly correlated with the activation of NF-κB, PI3K, and MAPK protein kinases nor the amount of pro-inflammatory cytokine (IL-1β, IL-6, and TNF-α) released in old murine BMMs." (PMID 40649955, 2025). "Interferon (IFN)-γ and interleukin-6 upregulation in the sera of MA10-infected mice, along with the absence of MA10 in the kidneys, implied that the kidneys were affected by the MA10 infection-induced cytokine storm rather than by direct MA10 infection of the kidneys." (PMID 38634132, 2024). "Early fever and high levels of CRP and inflammatory cytokines IL-6, TNF-α, and IFN-γ, as seen in our LE patients in the absence of infection, strongly resemble cytokine release syndrome, which may result in multiorgan dysfunction involving the brain, lung, and kidney." (PMID 37626859, 2023).
infection (continued). "The reduced levels of early-response cytokines (IL-6, IL-1β, and TNF-α) following LDRT after infection on both day 1 and 3 were increased in the anti-TGF-β mAb-treated group, which was similar to the levels in virus-infected mice without LDRT (infection + mouse IgG group)." (PMID 37304302, 2023). "Co-stimulation of SARS-CoV-2 S protein with the TLR2 ligand PAM3csk4, increased significantly the expression of the inflammatory mediators CXCL5, PAI-1 and IFNα at 12 hours following infection, but could not change the decreased production of the pro-inflammatory cytokines IL8, IL6 and TNFα." (PMID 36389723, 2022). "Despite not controlling the increase in IL-6 and IFN-γ, inhibition of HO-1 significantly reduced TNF levels when compared with pregnant infected mice treated with vehicle (p=0.0392), suggesting that ZnPPIX is able to control, at least in part, infection-induced inflammation at implantation sites." (PMID 35619717, 2022). "The unchanged high Colony-forming Units (CFU) in lavage, the significant differences in Interleukin (IL)-6 in blood compared to lavage and the lack of increase in Alkaline Phosphates (ALP) in serum over the entire observation period show the constant local infection." (PMID 35201371, 2022). "The excessive uncontrolled inflammatory responses mainly led by IL-6, IFNγ, TNFα, CRP, D-dimer, VES, and the lack of vitamin D (pre-hormone D) were common clinical traits of this infection, though those parameters were common to other types of lung diseases and infections." (PMID 36428884, 2022). "Therefore, we monitored the levels of IL-6, IFN-γ, IL-2, IL-10, TGF-β, TNF-α, IL-12, and IL-17 in the lung lysates of M. tb-infected mice with and without L-GSH treatment at varying stages of the infection to assess the granulomatous response." (PMID 35453358, 2022). "In vitro, MPXV infection of human cells does not induce interferon-stimulated gene (ISG) expression and further suppresses Tumour Necrosis Factor alpha (TNF-α), Interleukin 1 alpha and beta (IL-1α and β), C-C Motif Chemokine Ligand 5 (CCL5) and Interleukin 6 (IL-6) activation in primary fibroblasts." (PMID 35887214, 2022). "Furthermore, gene expression analysis was performed to investigate the involvement of certain receptors and intracellular signalling molecules following infection of keratinocytes with S. aureus, in the presence or absence of PLNC8 αβ, and to verify the results of IL-6 and CXCL8 on the mRNA level." (PMID 34131160, 2021). "It has been reported that the concentration of IL-6 is increased in the amniotic fluid, cervical vaginal fluid, fetal membranes, decidua, myometrium, and cervix in PTB and pPROM, both in cases of microbial invasion of the intraamniotic cavity (MIAC) as well as in the absence of infection." (PMID 32848846, 2020). "It was found in this study that HTV MV, in the absence of infection, with different levels of TLR4-targeted mice and treatments could result in different impacts on pro-inflammatory cytokine levels, such as IL-6 and MIP-2, in the BALF and in the systemic circulation." (PMID 32130574, 2020). "Moreover, cervico-vaginal lavages (CVL) of HIV infected women sampled within weeks of infection had significantly elevated levels of IL-6, IL-10, and IL-12, compared to HIV negative women whereas, IL-1α, IL-1β, IL-8, IL-6, IP10 and IL-10 were increased in plasma of the same patients." (PMID 32615983, 2020). "However, whether IL-6 also participates in the differentiation and expansion of TH17 cells after aerosol infection with Mtb has not been elucidated so far." (PMID 33375150, 2020). "Furthermore, the levels of interleukin (IL)-2, IL-4, IL-6, IL-22, and interferon (IFN)-γ, but not that of tumor necrosis factor alpha (TNF-α), IL-10, and IL-9, increased to their highest levels at day 4 post-infection and decreased thereafter." (PMID 31711531, 2019).